RN7SKP155 (RN7SK pseudogene 155)
Gene: Miscellaneous RNA gene on chromosome 8 (123,588,759 to 123,589,046, forward strand). Ensembl gene ENSG00000251840.
Homologues: Orthologues: mouse Gm56185 (40% identical). Paralogues in human: RN7SKP25 (56% identical), RN7SKP189 (55% identical), 7SK (55% identical), RN7SKP10 (55% identical), RN7SKP211 (55% identical), RN7SKP225 (55% identical), RN7SKP79 (55% identical), RN7SKP180 (54% identical), RN7SKP203 (54% identical), RN7SKP243 (54% identical), RN7SKP250 (54% identical), RN7SKP269 (54% identical), and 282 more.